CCL20 (C-C motif chemokine ligand 20)
Diseases named in the same sentence as CCL20 in open-access papers (continued):
Sharing a sentence is not in itself a finding about the gene and the disease.
lung adenocarcinoma (19 papers, 2011 to 2025). A carcinoma that arises from the lung and is characterized by the presence of malignant glandular epithelial cells. "Using Kaplan-Meier analysis, we looked for associations between the clinical course of lung adenocarcinoma patients and the extent of CCL20/CCR6 staining in their tumor samples." (PMID 21949768, 2011). "In lung adenocarcinoma, high expression of CCL20, IL23A, MMP1 and MMP3 was significantly associated with poor patient prognosis, whereas high expression of FOS, HLA-DPA1, HLA-DPB1, HLA-DQA1, HLA-DQB1 and HLA-DRA was significantly associated with improved patient prognosis." (PMID 40016789, 2025). "The modification of CAR-T cells targeting the lung adenocarcinoma antigen MUC1 for the chemokine receptor CCR6 enhanced migration toward tumor sites rich in CCL20 and CAR-T cell efficacy." (PMID 41181132, 2025). "We used TCGA and GTEx database to analyze the relationship between the expression levels of CXCL13 and CCL20 and the overall survival rate in patients with lung adenocarcinoma (LUAD)." (PMID 40764989, 2025). "To validate these findings, we analyzed the transcriptional and protein expression levels of HER2, CXCL13, and CCL20 in six pairs of clinical lung adenocarcinoma tissue samples." (PMID 40764989, 2025). "Our analysis of 483 LUAD samples and 347 normal tissue samples from the TCGA and GTEx databases revealed that the expression levels of CXCL13 and CCL20 in lung adenocarcinoma tissues were significantly higher compared to normal lung tissues." (PMID 40764989, 2025). "In lung adenocarcinoma, CCL20 promotes tumor progression by increasing the epithelial–mesenchymal transition (EMT), facilitating invasion, and metastasizing." (PMID 39273632, 2024). "It is noteworthy that CCL20 exhibits a promotive role in tumor development, specifically in lung adenocarcinoma, by promoting the epithelial-mesenchymal transition process." (PMID 38491375, 2024). "C-C motif chemokine ligand 20 (CCL20) participates in multiple oncogenic processes, but its role in lung adenocarcinoma (LUAD) is unclear." (PMID 35864953, 2022). "The results of Western blotting showed that BTG2, TLR2, and IL7R proteins were markedly downregulated in lung adenocarcinoma cell line A549, while CCL20 protein was markedly upregulated." (PMID 35372503, 2022). "CCL20/ERK signaling has been further investigated in lung adenocarcinoma samples obtained at surgery and cell lines and assessed for the expression, tissue localization, and production." (PMID 32707869, 2020). "Immunohistochemistry studies indicated that the majority of lung adenocarcinoma tumor samples highly stained for CCL20, while only a minority highly expressed CCR6." (PMID 21949768, 2011). "CCL20 expression was a risk factor and significantly negatively correlated with overall survival in cervical squamous cell carcinoma, kidney renal papillary cell carcinoma (KIRP), uveal melanoma, and lung adenocarcinoma (LUAD)." (PMID 38914792, 2024). "Collectively, the findings suggest that CCR6 and CCL20 may serve a role in lung adenocarcinoma, leading to proliferation and migration via autocrine or paracrine mechanisms." (PMID 32707869, 2020). "Similarly, Stk24 silencing inhibited the IL-17-induced expression of IL-6, CXCL2, and CCL20 in human lung adenocarcinoma cells A549." (PMID 29760709, 2018). "The corresponding chemokines (CCL20 and CXCL13) are high-expressed in lung adenocarcinoma and squamous cell carcinoma." (PMID 33777013, 2021). "CCL20/CCR6 interactions can lead to proliferation and migration dependent in part on extracellular signal-regulated kinase (ERK) phosphorylation during lung adenocarcinoma growth." (PMID 29788995, 2018). "Using immunohistochemistry, we defined the expression patterns of CCL20 and CCR6 in lung adenocarcinoma." (PMID 21949768, 2011).
lung adenocarcinoma (continued). "To study the clinical relevance of CCL20/CCR6 expression in NSCLC, we tested the expression of the chemokine and receptor in 49 lung adenocarcinoma tissue samples removed during surgery." (PMID 21949768, 2011). "No reports indicated an up-regulation of CCL20 in the dysplastic lesion, but it has been reported to be up-regulated in lung adenocarcinoma as a poor prognostic marker." (PMID 39273632, 2024). "Finally, seven copper death genes related to lung adenocarcinoma were screened out, including ARHGEF39, EFCC1, SERPIND1, INSL4, ANLN, RHOV and CCL20." (PMID 36313444, 2022). "We identified four biomarkers (MAP3K8, CCL20, VEGFC, and ANGPTL4) that could predict overall survival in lung adenocarcinoma (HR = 1.98, 95% CI 1.48 to 2.64, P = 4.19e−06) and this model could be used as a classifier for the evaluation of low-risk and high-risk groups." (PMID 32019546, 2020).
glioma (18 papers, 2013 to 2025). A benign or malignant brain and spinal cord tumor that arises from glial cells (astrocytes, oligodendrocytes, ependymal cells). "As the sole cytokines incorporated into the construction of GA-MSCRGPI, C–C motif chemokine ligand 20 (CCL20) encodes a ligand for the C–C chemokine receptor CCR6 involved in immunomodulation of glioma cells." (PMID 37005685, 2023). "In glioma, CCL20 upregulated by ZNF395 enhanced M2 macrophage polarization which in turn promoted the proliferation of glioma cells." (PMID 39985603, 2025). "CXCL14 was expressed mainly by a diverse group of glioma cells, while CCL20, in contrast, was mainly expressed by myeloid cells and T lymphocytes." (PMID 39272976, 2024). "FDPS was confirmed to promote prostate cancer progression and glioma growth through modulation of small GTPases/AKT axis or regulating CCL20 via the Wnt/β-catenin signaling pathway." (PMID 37406019, 2023). "Taken together, these findings indicated that ADO induces the NF-κB pathway to enhance CCL20 production to drive glioma tumorigenesis and progression." (PMID 33483477, 2021). "Collectively, the results suggest that the ADO-hypotaurine axis targets the NF-κB pathway to promote CCL20 expression and activity in glioma tumorigenesis and progression." (PMID 33483477, 2021). "Glioma tumor cells release CCL20 and induce CCL2 production in TAMs and GAMs attracting MDSCs into TME." (PMID 33919732, 2021). "Using transcription profiling, we further uncovered that the ADO/hypotaurine axis targets CCL20 secretion through activating the NF-κB pathway to drive the self-renewal and maintenance of glioma ‘cancer stem cells’ or glioma cancer stem-like cells." (PMID 33483477, 2021). "Consistently, patients with high levels of ADO were usually accompanied by an overexpression of CCL20 and its only known receptor CCR627,28, whereas low ADO expression was associated with low levels of CCL20 and CCR6 in gliomas." (PMID 33483477, 2021). "This cross-talk between NF-κB and CCL20 drives tumor progression and promotes cancer stemness in multiple malignancies including glioma." (PMID 33483477, 2021). "In fact, in a glioma model, it has been shown that CCL20 [chemokine C-C motif ligand 20) is released by astrocytes in response to hypoxia and, by stimulating the CCR6-NF-κB signaling pathway, further enhances the HIF-1-mediated hypoxic response." (PMID 33066172, 2020). "Our results indicated that FDPS is up‐regulated in glioma tissues compared with normal tissues and that FDPS overexpression promotes glioma proliferation and TAMs recruitment by regulating CCL20." (PMID 32596949, 2020). "Pathway analysis illustrated that Wnt/β‐catenin signalling pathway is involved in CCL20 induction and TAMs recruitment in glioma." (PMID 32596949, 2020). "We show that increased levels of CCL20 released from cancer cells significantly induce EMT under hypoxic stress in glioma cells, while melatonin can reverse this transition." (PMID 29212174, 2017). "In glioma tissues, CCL20 and its receptor, CCR6 protein levels are upregulated, compared with their expression in non-neoplastic brain tissues." (PMID 29212174, 2017). "In addition, CCL20 can be released by astrocytes to assist gliomas in counteracting hypoxia by binding to CCR6 to activate the NF-κB pathway and to upregulate HIF-1 expression." (PMID 40243478, 2025). "In addition, the accumulating CCL20 also further stimulates the NF-κB pathway to form a feedforward loop to promote glioma stem cell (GSC) renewal and maintenance." (PMID 33483477, 2021). "In consequence, it is likely that the high levels of CCL20 induced by ADO through the hypotaurine/NF-κB signaling axis in glioma may also function with NF-κB in a positive feedforward loop to promote cancer stemness and drive tumor progression." (PMID 33483477, 2021). "Together, we conclude that CCL20 is required for FDPS‐mediated macrophage infiltration in glioma." (PMID 32596949, 2020).
glioma (continued). "Moreover, FDPS‐induced CCL20 modulated the tumour microenvironment through TAMs infiltration in glioma tissues." (PMID 32596949, 2020). "Collectively, these results indicate that CCL20 might be an important mediator of melatonin-mediated EMT in glioma cells." (PMID 29212174, 2017). "Considering that the change in CCL20 transcript levels is regulated by melatonin, we speculated that melatonin might block the signal transduction of TGFβ/Smad to suppress glioma cell EMT under hypoxia." (PMID 29212174, 2017). "In this study, we investigated the roles of melatonin in hypoxia-induced EMT suppression, and found that melatonin could significantly suppress the release of the cytokine, CCL20, from cancer cells and antagonize glioma cell metastasis and invasion under hypoxic stress in glioma cells." (PMID 29212174, 2017). "Among the available evidence, glioma-reactive astrocytes can secrete a variety of cytokines and chemokines, including IGF1, CCL20, TGF-β, IL-10, IL-12, IL1A/B, IL-2, CXCL10, and G-CSF." (PMID 40243478, 2025). "U87 glioma cells express several chemokines (CCL2, CCL20, CXCL1, CXCL2, CXCL8, etc.), among which IL-8 is the most abundant after radiation." (PMID 31488817, 2019). "We also found that the CSF concentrations of CCL20 in glioma patients were significantly higher compared to nontumor patients." (PMID 33483477, 2021). "Interestingly, only CCL20 displayed a significant difference (significant; *p = 0.01) in levels between glioma and nontumor patients." (PMID 33483477, 2021). "Furthermore, our findings show that melatonin deregulates Smad7 expression to suppress TGFβ/Smad-mediated increase in CCL20 transcript levels and CCL20-induced EMT occurrence, suggesting a potential anti-EMT therapeutic role for melatonin in malignant transformation in gliomas." (PMID 29212174, 2017). "However, the relationship between CCL20 and melatonin-mediated anti-EMT in glioma cells remains unclear." (PMID 29212174, 2017). "Furthermore, our findings show that melatonin deregulates Smad7 expression to suppress TGFβ/Smad-mediated increase in CCL20 transcript levels and CCL20-induced EMT occurrence, suggesting potential anti-EMT therapeutic strategy of melatonin to overcome malignant transformation in gliomas." (PMID 29212174, 2017). "In summary, our study provides data that clearly show that melatonin induces Smad7 expression leading to suppression of TGFβ/Smad-CCL20 activities and EMT in gliomas, indicating that melatonin may be used as a novel therapeutic to treat malignant transformation in gliomas." (PMID 29212174, 2017). "The original RNA-seq results suggested that glioma patients have higher levels of CCL20, CXCL1, CXCL2, CXCL5, and CXCL16 compared to noncancerous patients and that the levels of these small chemotactic cytokines in glioma are correlated with malignancy." (PMID 33483477, 2021). "The results showed that there were trends linking these cytokines, CCL20, CXCL1, CXCL2, CXCL5, and CXCL16, to ADO expression in gliomas but these correlations were not significant, probably due to the low number of patients recruited to the study." (PMID 33483477, 2021).
inflammatory bowel disease (17 papers, 2009 to 2025). A spectrum of small and large bowel inflammatory diseases of unknown etiology. "Multivariable linear regression analyses revealed that both the diagnosis of inflammatory bowel disease and vitamin D deficiency were independently associated with elevated CCL20 levels." (PMID 40542081, 2025). "Intestinal epithelial overexpression of the Th17 cell chemoattractant CCL20 is implicated in inflammatory bowel disease and influenced by NOD2 mutations in Crohn’s disease." (PMID 40542081, 2025). "The C-C motif chemokine 20 protein encoded by CCL20 is an important Th17 mediator that is involved in inflammatory bowel disease, indicating that CCL20 may be associated with immune function." (PMID 33971621, 2021). "The chemokine CCL20 is expressed in the gastrointestinal tract under proinflammatory conditions such as infections and inflammatory bowel disease." (PMID 39728373, 2024). "CCL20, located on chromosome 2, is significantly enriched in GWAS signaling in inflammatory bowel disease and was identified as a gene specifically expressed in human and porcine monocyte (TAU_human = 0.94, TAU_pig = 0.87)." (PMID 39054472, 2024). "The chemokine C-C motif ligand 20 (CCL20) is increased in the colonic mucosa during active inflammatory bowel disease (IBD) and can be found both in the epithelium and immune cells in the lamina propria." (PMID 30347808, 2018). "The colonic epithelium has been demonstrated as a major source of CCL20 and epithelial expression of this chemokine is elevated in inflammatory bowel disease." (PMID 19814810, 2009). "CCL20 expression is upregulated in a variety of inflammatory disorders including appendicitis, atopic dermatitis, rheumatoid arthritis, and inflammatory bowel diseases such as Crohn's disease." (PMID 19814810, 2009). "For instance, the presence of inflammatory mediators promotes the up-regulation of CCL20 in mucosal epithelial cells; other studies have also demonstrated that the colonic epithelial cells from patients with inflammatory bowel disease produce higher level of CCL20." (PMID 28830557, 2017). "CCL20 can be induced by pro-inflammatory signals such as TNF-α or TLR, bind CCR6 and induce the recruitment of B cells with high CCL6 expression into intestinal epithelial cells of patients with inflammatory bowel disease in response to inflammatory stimuli." (PMID 36419192, 2022). "The chemokine CCL20 and its receptor CCR6 are putative drug targets in inflammatory bowel disease, and CCL20 is a novel IBD predilection gene." (PMID 26536229, 2015).
prostate carcinoma (17 papers, 2009 to 2025). A carcinoma that arises from epithelial cells of the prostate gland. "In the same study, autophagy-induced CCL20 expression in tumor cells further potentiated the invasiveness of prostate cancer cells by promoting the infiltration and polarization of M2 macrophages." (PMID 39985603, 2025). "In prostate cancer expression, CCL20 in macrophages and monocytes was found to suppress antitumor immunity of T cells leading to bone marrow metastasis." (PMID 39985603, 2025). "Expression of CXCL8, CCL2, CXCL10, and CCL20 is dependent on NF-κB activation in prostate cancer cells expressing low levels of SFMBT2." (PMID 32971847, 2020). "One study has shown that the chemokine receptor CXCR4 stimulates the production of the chemokine CCL20 and that CCL20 stimulates the proliferation and adhesion to collagen of prostate cancer cells." (PMID 32707869, 2020). "We found that the down-regulation of SFMBT2 promotes the infiltration of preadipocytes and TAMs through up-regulation of CXCL8, CCL2, CXCL10, and CCL20 expression in prostate cancer." (PMID 32971847, 2020). "Expression of CXCL8, CCL2, CXCL10, and CCL20 was also elevated in prostate cancer patients having a higher Gleason score (≥8), which had substantially lower SFMBT2 expression." (PMID 32971847, 2020). "Our analysis indicated the high expression of CXCL8, CCL2, CXCL10, and CCL20 in prostate cancer tissues expressing a low expression level of SFMBT2, which is correlated with high Gleason scores." (PMID 32971847, 2020). "Expression levels of CXCL8, CCL2, CXCL10, and CCL20 in prostate cancer with Gleason scores of ≥8 were higher than those with Gleason scores of ≤7." (PMID 32971847, 2020). "We also found that the up-regulation of CXCL8, CCL2, CXCL10, and CCL20 expression is dependent on NF-κB activation in prostate cancer cells expressing a low level of SFMBT2." (PMID 32971847, 2020). "We found that the down-regulation of SFMBT2 promotes the up-regulation of CXCL8, CCL2, CXCL10, and CCL20 expression in prostate cancer cells, resulting in elevated infiltration of preadipocytes and TAMs." (PMID 32971847, 2020). "To further study the possible role of CXCR4 in the regulation of CCL20 expression, we evaluated the mRNA expression of CCL20 in prostate cancer cells with low and high CXCR4 expression using real-time RT-PCR." (PMID 19340288, 2009). "To better understand the role of CCL20 in prostate cancer development, we characterized the expression of CCL20 and its receptor CCR6 in human prostate cell lines PC3, LNCaP, 22RV1 and DU145." (PMID 19340288, 2009). "Furthermore, blockade of CCL20 also resulted in higher survival of mice with prostate cancer bone metastasis." (PMID 36836690, 2023). "In addition to CXCL12, other studies have also implicated cytokine CCL20 and its receptor CCR6 for their involvement in prostate cancer bone metastasis." (PMID 36836690, 2023). "Over-expression of CCL20 has been found in prostate cancer and it promotes tumor growth." (PMID 32971847, 2020). "However, roles of CXCL10 and CCL20 in different cell types are not fully understood in prostate cancer at present." (PMID 32971847, 2020). "Also, the expression level of CXCL8, CCL2, CXCL10, and CCL20 was proportionally related to a high Gleason score of ≥8, which seems closely related to prostate cancer invasion and metastasis." (PMID 32971847, 2020). "Furthermore, overexpression of CCL20 in prostate cancer cells promotes growth and adhesion in vitro and increases tumor growth and invasiveness in the in vivo mouse model." (PMID 32707869, 2020). "We observed the increased expression of CXCL8, CCL2, CXCL10, and CCL20 in prostate cancer tissues induced by intraprostatic injection of LNCaP cells stably transfected with SFMBT2 shRNA compared with prostate tissues injected with LNCaP cells stably transfected with control shRNA." (PMID 32971847, 2020). "Overexpression of CCL20 in prostate cancer cells promoted tumor growth and invasiveness." (PMID 27723802, 2016).